HSPD1 (heat shock protein family D (Hsp60) member 1)
Diseases named in the same sentence as HSPD1 in open-access papers (continued):
Sharing a sentence is not in itself a finding about the gene and the disease.
prostate carcinoma (7 papers, 2019 to 2026). A carcinoma that arises from epithelial cells of the prostate gland. "HSPD1 is a mitochondrial chaperone involved in anti-apoptosis and prostate cancer progression." (PMID 33801459, 2021). "Antibodies against HSPD1, HSPA5 and ATP5B were added to the panel as they had been previously identified specifically in LEVs compared to exosomes, in addition to being associated with prostate cancer progression." (PMID 33801459, 2021). "Inhibitors of the mitochondrial unfolded protein response targeting HSPD1 induced accumulation and metabolic stress of polyubiquitinated proteins, thereby inhibiting AKT/mTOR signaling in prostate cancer." (PMID 39430254, 2024). "Mitochondrial unfolded protein response inhibitors targeting HSPD1 induced accumulation of poly-ubiquitinated proteins and metabolic stress, thereby suppressing AKT/mTOR signaling in prostate cancer." (PMID 39430254, 2024).
oral squamous cell carcinoma (6 papers, 2019 to 2024). "HSPD1 promotes cell invasion and migration, which contributes to the poor prognosis in oral squamous cell carcinoma." (PMID 34712697, 2021).
Spastic paraplegia (6 papers, 2009 to 2022). Complete loss of the ability to move the lower limbs accompanied by spasticity of the lower limbs. "Yet, another study showed that the mutations in HSPD1, the gene encoding Hsp60, are related to two human inherited diseases of the nervous system, spastic paraplegia and MitCHAP60 disease." (PMID 27803687, 2016). "The detected proteins are involved in a wide range of diseases; spastic paraplegia (HSPD1), cancer (BAX, PHB), optic atrophy (OPA1), ethylmalonic encephalopathy (ETHE1) and Parkinson's disease (NDUFV2)." (PMID 19476632, 2009).
COVID-19 (5 papers, 2021 to 2025). A disease caused by infection with severe acute respiratory syndrome coronavirus 2. "High concentrations of circulatory HSPD1 in severe COVID-19 patients are associated with cardiac failure and are a potential clinical biomarker for heart disorders in COVID-19 patients." (PMID 34975885, 2021). "The coronavirus disease 2019 (COVID-19), the SARS-CoV-2-induced pandemic, has highlighted new implications of Hsp60 in inflammatory responses and disease pathogenesis, with single-cell RNA sequencing studies revealing upregulation of HSPD1 in alveolar macrophages of severe COVID-19 patients." (PMID 41007425, 2025). "Indeed, it was reported that the HSPD1-derived altered peptide ligand reduced the pro-inflammatory cytokines in rheumatoid arthritis disease and also in COVID-19 patients; in addition, HSPE1 inhibited lipopolysaccharide-induced inflammation by interacting with HSPD1." (PMID 38200905, 2024).
gastric cancer (5 papers, 2014 to 2024). A primary or metastatic malignant neoplasm involving the stomach. "Comparison between normal stomach tissue and stomach tumors showed that CST1 (p = 3.97E−21), INHBA (p = 9.22E−20), ACAN (p = 1.08E−19), HSP90AB1 (p = 2.62E−19), and HSPD1 (p = 3.91E−19) were the leading five genes that were overexpressed in stomach cancer." (PMID 33828156, 2021). "Our analysis showed that compared with normal stomach tissue, CST1, INHBA, ACAN, HSP90AB1, and HSPD1 were the leading five genes that were overexpressed in stomach cancer." (PMID 33828156, 2021). "The stage-based assessment of overexpressed genes showed significant upregulation of CST1, INHBA, ACAN, HSP90AB1, and HSPD1 genes across all stages, including early, locally advanced and metastatic stomach cancer." (PMID 33828156, 2021).
cardiac failure (4 papers, 2020 to 2021). "It has been already reported that high levels of circulatory HSPD1 are associated with cardiac failures." (PMID 33995121, 2021).
glioblastoma (4 papers, 2019 to 2024). The most malignant astrocytic tumor (WHO grade IV). "KHS101 is a synthetic small molecule reported to impair the growth of glioblastoma cells in vitro and in vivo via inhibition of HSPD1 chaperone activity." (PMID 34364401, 2021). "KHS101 promotes HSPD1 aggregation thereby altering the metabolic activity of glioblastoma cells." (PMID 34364401, 2021).
glioma (4 papers, 2014 to 2023). A benign or malignant brain and spinal cord tumor that arises from glial cells (astrocytes, oligodendrocytes, ependymal cells). "HSPD1 encodes a mitochondrial chaperone promoting cell immortality and proliferation; notably, its inhibition by curcumin has been associated with anti-glioma effects in vitro." (PMID 37755981, 2023).
head and neck cancer (4 papers, 2020 to 2022). A primary or metastatic malignant neoplasm affecting the head and neck. "Fan and his team detected the expression pattern of HSPD1 in head and neck cancer specimens and observed that its downregulation was related to dismal patient outcome." (PMID 35342421, 2022). "Previous analysis illustrated that frequent mutations of HSPH1, HSPD1, HSPA4 and HSP90AA1 were detected in head and neck cancer in head and neck squamous carcinoma." (PMID 34712697, 2021).
ovarian carcinoma (4 papers, 2014 to 2025). A malignant neoplasm originating from the surface ovarian epithelium. "Hierarchical clustering indicated that kidney and ovarian cancer subtypes were clustered together and displayed the strongest and most significant associations between high HSPD1 expression and sensitivity to DNA rep." (PMID 37508418, 2023). "Low HSPD1 (Heat Shock Protein Family D (HSP60) Member 1) expression was associated with unfavorable prognosis in ovarian cancer patients." (PMID 37087461, 2023). "As to the association between HSPD1 expression status and the prognosis of patients, there are also conflicting reports in ovarian cancer studies." (PMID 37087461, 2023). "We confirmed experimentally that the expression of HSPD1 is associated with an increased sensitivity of ovarian cancer cells to drugs targeting mitosis and a reduced sensitivity to drugs promoting apoptosis." (PMID 37508418, 2023). "We noticed that cell lines originating from ovarian and kidney cancer contributed the most to the Sen-Scoreglobal for these drug classes, as in ovarian cancer cell lines, high HSPD1 expression was significantly associated with sensitivity to 39% of DNA rep." (PMID 37508418, 2023). "To validate the results of our pipeline in culture, we used ovarian cancer cell lines to explore whether a high level of HSPD1 is indeed associated with sensitivity to chemotherapy." (PMID 37508418, 2023). "We identified HSPD1—previously recognized as prognostic in ovarian cancer based on TCGA data—was also identified as spMOCA’s hub genes across all four cancer types." (PMID 41370198, 2025). "Previous studies have confirmed the prognostic relevance of HSPD1 in ovarian cancer, aligning the findings from TCGA data." (PMID 41370198, 2025). "siRNA-mediated and lentiviral vector-mediated transfection were used to determine the effect of HSPD1 knockdown in ovarian cancer cells." (PMID 37087461, 2023). "HSPD1 was shown to promote oxidative phosphorylation (OXPHOS) in ovarian cancer, as HSPD1 knockdown disrupted mitochondrial integrity and suppressed OXPHOS." (PMID 37508418, 2023). "The results showed that downregulation of HSPD1 via siRNA or LV-shRNA significantly promoted the proliferation ability of ovarian cancer cells (P = 0.003, 0.03, 0.02, respectively)." (PMID 37087461, 2023). "To further understand the effects of HSPD1 deletion on ovarian cancer cells, we performed quantitative proteomic analysis." (PMID 37087461, 2023). "Specifically, we first measured the expression levels of HSPD1 in four ovarian cancer cell lines using Western blot analysis." (PMID 37508418, 2023). "Knockdown of HSPD1 significantly promoted the proliferation and migration of ovarian cancer cells." (PMID 37087461, 2023). "In testing whether high HSPD1 expression sensitizes ovarian cancer cells to cisplatin, a drug targeting proliferation, we found that cells with higher HSPD1 expression were indeed more sensitive." (PMID 37508418, 2023). "Furthermore, to explore the role of HSPD1 in ovarian cancer development, we isolated the mitochondria and evaluated the differential expression of HSPD1 by western blot analysis in one normal ovarian epithelial cell line and four ovarian cancer cell lines." (PMID 37087461, 2023). "Furthermore, HSPD1 knockdown stable cell lines (sh-HSPD1) also showed increased migration capacities compared with cells transfected with empty vector lentivirus (sh-NC) The results suggested that HSP60 may inhibit the migration of specific ovarian cancer cell." (PMID 37087461, 2023). "Collectively, these findings showed that HSPD1 knockdown could inhibit the LA synthesis mediated by OXSM, which led to promotion of ovarian cancer cell proliferation." (PMID 37087461, 2023).
schizophrenia (4 papers, 2019 to 2024). A major psychotic disorder characterized by abnormalities in the perception or expression of reality. "Genes that were associated with brain volumes, depression, and schizophrenia or bipolar disorder includedAC011997.1,AKT3,BANK1,BOLL,DCC,HSPD1,HSPE1,HSPE1-MOB4,MOB4,PLCL1,RFTN2,SF3B1, andTRPS1." (PMID 40800518, 2024). "We illustrate multiple isoTWAS associations undetectable at the gene-level, prioritizing isoforms of AKT3, CUL3 and HSPD1 in schizophrenia and PCLO with multiple disorders." (PMID 38036788, 2023). "A genome-wide association study found that six immune candidates, namely, DPP4, HSPD1, EGR1, CLU, ESAM, and NFATC3, were associated with schizophrenia." (PMID 35757702, 2022).
depression (3 papers, 2013 to 2024). "Although a role for these particular heat-shock proteins in human depression has yet to be identified, preclinical models have identified HSPA8 and HSPD1 as proteins regulated subsequent to chronic stress." (PMID 24040027, 2013).
glaucoma (3 papers, 2019 to 2021). Increased pressure in the eyeball due to obstruction of the outflow of aqueous humor. "Antibodies against the 60 kDa heat shock protein, encoded by HSPD1, were amongst the first to be detected in connection with glaucoma and are consistently increased throughout different study populations." (PMID 30899261, 2019). "All markers, except HSPD1, were suitable to distinguish mild forms of glaucoma from healthy subjects." (PMID 34943212, 2021). "While antibodies to HSPD1 (mitochondrial 60 kDa heat shock protein) have frequently been observed in association with glaucoma, AAbs to C1QBP, TARS and PNMA2 have not yet been described in the disease context." (PMID 32140226, 2020). "Furthermore, some previous identified glaucoma autoantigens including heat shock protein 60 dDA (HSPD1), heat shock protein 70 kDa (HSPA1B), vimentin (VIM), α-enolase (ENO1) and superoxide dismutase 1 (SOD1) could be detected." (PMID 30899261, 2019). "Therefore, we wanted to evaluate whether validated glaucoma‐related AAbs to PNMA2, TARS, C1QBP and HSPD1 hold the potential to serve as biomarker candidates." (PMID 32140226, 2020).
hypomyelinating leukodystrophy 4 (3 papers, 2015 to 2019). Any leukodystrophy in which the cause of the disease is a mutation in the HSPD1 gene. "Similarly, heterozygous mutations in HSPD1 lead to SPG13, but homozygous missense mutations of the same gene are implicated in hypomyelinating leukodystrophy type 4." (PMID 25758904, 2015).
osteosarcoma (3 papers, 2013 to 2024). A usually aggressive malignant bone-forming mesenchymal neoplasm, predominantly affecting adolescents and young adults. "Based on multi-omics analysis and preliminary experiments, we determined that aberrant overexpression of HSPD1 is strongly associated with impaired outcomes in osteosarcoma and acts as a tumor promoter." (PMID 39430254, 2024). "HSPD1 is aberrantly upregulated in osteosarcoma and associated with shorter OS times." (PMID 39430254, 2024). "Taken together, these data suggest that HSPD1 knockdown significantly inhibited the malignant biological behavior of osteosarcoma and enhanced apoptosis." (PMID 39430254, 2024). "Further, in vitro functional rescue experiments and WB assays have shown that HSPD1 promotes the proliferation and invasion of osteosarcoma cells through ATP5A1-mediated activation of mTOR signaling." (PMID 39430254, 2024). "We further investigated the involvement of ATP5A1 in the mechanism of HSPD1-promoted osteosarcoma progression using several in vitro functional rescue assays." (PMID 39430254, 2024). "Bulk RNA-seq data indicated a notable increase in HSPD1 expression in osteosarcoma tissues compared to normal tissues." (PMID 39430254, 2024). "MK2206 treatment significantly reduced the levels of p-AKT, p-mTOR, N-cadherin, and vimentin in osteosarcoma cells, while overexpression of HSPD1 partially abrogated these inhibitory effects." (PMID 39430254, 2024). "HSPD1 upregulation in osteosarcoma cells significantly promoted cell viability and increased the number and size of colony formation compared with vector controls." (PMID 39430254, 2024). "The results of WB analysis showed that overexpressed HSPD1 suppressed the expression of E-cadherin, and enhanced the expression of N-cadherin and vimentin in osteosarcoma cells." (PMID 39430254, 2024). "Meanwhile, flow cytometry experiments revealed that HSPD1 knockdown induced cell cycle arrest mainly in the G0/G1 phase, along with a decline in the S phase of osteosarcoma cells, compared with controls." (PMID 39430254, 2024). "Collectively, the in vivo and ex vivo outcomes indicated that HSPD1 facilitated osteosarcoma cell proliferation." (PMID 39430254, 2024). "In contrast, elevated HSPD1 and DNAJC1 expression were associated with inferior outcomes in osteosarcoma." (PMID 39430254, 2024). "Comparing HSPD1 expression in normal osteoblasts (hFOB1.19) against each of the three different osteosarcoma cells (U2OS, MG63, and MNNG/HOS) revealed significant upregulation of the gene in tumor." (PMID 39430254, 2024). "Accordingly, the present study is dedicated to elucidating the specific function and mechanism of HSPD1 in osteosarcoma." (PMID 39430254, 2024). "Considering that HSPD1 not only had the highest hazard ratios in univariate Cox regression but also the highest positive coefficients in the HSP-derived scoring system, we next focused on analyzing the multi-omics data of HSPD1 in osteosarcoma." (PMID 39430254, 2024). "Despite our findings on the oncogenic properties of HSPD1 in osteosarcoma, there is still much to be explored in the future." (PMID 39430254, 2024). "In this study, Western blot confirmed that knockdown of HSPD1 in osteosarcoma cells triggered a decrease in Vimentin and N-cadherin and an upregulation of E-cadherin." (PMID 39430254, 2024). "Next, we tested the effect of HSPD1 on ATP5A1 ubiquitination and observed that HSPD1 overexpression inhibited ATP5A1 polyubiquitination, whereas HSPD1 depletion increased ATP5A1 ubiquitination levels in osteosarcoma cells." (PMID 39430254, 2024). "GSEA analysis based on HSPD1 transcript expression from all osteosarcoma patients in the training and validation cohorts showed that the positively regulated gene set by mTOR signaling (MTOR_UP.N4.V1_UP) was enriched significantly in HSPD1-overexpressing cohorts." (PMID 39430254, 2024).
osteosarcoma (continued). "Expression levels of p-AKT and p-mTOR were increased upon ATP5A1 upregulation, and importantly, the inhibition of phosphorylation levels of biomarkers within the mTOR pathway in HSPD1 knockdown osteosarcoma cells was partially reversed by exogenous expression of ATP5A1." (PMID 39430254, 2024). "Nevertheless, the relationship between the function of HSPD1 and the progression of osteosarcoma remains unclear." (PMID 39430254, 2024). "GSEA analysis based on HSPD1 transcript expression in osteosarcoma cohorts revealed that the gene set positively regulated by mTOR signaling (MTOR_UP.N4.V1_UP) was significantly enriched in the HSPD1-overexpressing cohorts, indicating that mTOR signaling is activated." (PMID 39430254, 2024). "Establishing osteosarcoma cell lines with stable HSPD1 knockdown was done to determine if HSPD1 could influence malignant behavior, and the effectiveness of the knockdown was confirmed." (PMID 39430254, 2024). "Our findings indicate that the overexpression of HSPD1 may facilitate osteosarcoma progression by promoting cell proliferation, colony formation, and metastasis while disrupting apoptosis." (PMID 39430254, 2024). "Consequently, further investigations are required to elucidate the precise function of HSPD1 in osteosarcoma, which will facilitate the comprehension of its specific mechanistic role across different cancer types." (PMID 39430254, 2024). "Furthermore, our study provides both ex vivo and in vivo evidence of the oncogenic properties of HSPD1 in osteosarcoma." (PMID 39430254, 2024). "Through in vitro and in vivo experiments, we systematically identified HSPD1 as an important contributor to the regulation of proliferation, metastasis, and apoptosis in osteosarcoma by promoting the epithelial-mesenchymal transition (EMT) and activating AKT/mTOR signaling." (PMID 39430254, 2024). "We hypothesized that HSPD1 might bind to ATP5A1 in osteosarcoma cells, which was further confirmed by coIP protein blotting." (PMID 39430254, 2024). "Furthermore, while HSPD1 silencing enhanced ATP5A1 K48-linked ubiquitination to reduce the levels of ATP5A1 protein, HSPD1 over-expression had the opposite effect in osteosarcoma cells." (PMID 39430254, 2024). "Thus, we hypothesized that the AKT/mTOR pathway could serve as a potential mechanism through which HSPD1 facilitates the advancement of osteosarcoma." (PMID 39430254, 2024). "More importantly, the re-introduction of HSPD1 expression significantly attenuated the ATP5A1 K48-linked ubiquitination in the HSPD1-silenced osteosarcoma cells, while HSPD1 silencing obviously rescued the ATP5A1 K48-linked ubiquitination in the HSPD1-overexpressing osteosarcoma cells." (PMID 39430254, 2024). "Notably, HSPD1 is upregulated in osteosarcoma tissues and cell lines and may serve as an independent prognostic marker." (PMID 39430254, 2024). "Mechanistically, HSPD1 may interact with ATP5A1 to reduce the K48-linked ubiquitination and degradation of ATP5A1, which ultimately activates the AKT/mTOR pathway to ensure osteosarcoma progression and EMT process." (PMID 39430254, 2024). "However, the precise mechanism by which HSPD1 regulates the progression of osteosarcoma remains unclear." (PMID 39430254, 2024). "Our study details the biological role of HSPD1 in vitro and in vivo, the corresponding functional mechanisms, and its potential relationship with ATP5A1 to identify possible treatment options for osteosarcoma." (PMID 39430254, 2024). "Mechanistically, HSPD1 has been demonstrated to promote EMT and osteosarcoma progression by inhibiting ATP5A1 ubiquitination-dependent degradation and activating downstream AKT/mTOR signaling." (PMID 39430254, 2024). "Concurrently, the absence of HSPD1 demonstrated a robust capacity to diminish tumorigenesis of osteosarcoma cells in vivo." (PMID 39430254, 2024).
osteosarcoma (continued). "We then asked whether ATP5A1 was involved in HSPD1-induced overactivation of the AKT/mTOR axis and the corresponding phenotypic changes in osteosarcoma." (PMID 39430254, 2024). "The expression level of HSPD1 was markedly increased in osteosarcoma, correlating with a negative prognosis." (PMID 39430254, 2024). "At the mechanistic level, our findings indicate that HSPD1 may interact with ATP5A1 and increase ATP5A1 protein levels, thereby activating the AKT/mTOR pathway to mediate osteosarcoma progression." (PMID 39430254, 2024). "Within the scRNA-seq information for osteosarcoma (GSE162454), HSPD1 was detected in both cancerous cells and non-cancerous cells like endothelial cells, CD4+ T conventional lymphocytes, macrophages, and plasmocytes." (PMID 39430254, 2024).